IL6 (interleukin 6)
Diseases named in the same sentence as IL6 in open-access papers (continued):
Sharing a sentence is not in itself a finding about the gene and the disease.
endometriosis (continued). "For example in endometriosis, serum IL-6 levels are increased in patients and high levels of IL-6 in peritoneal fluid are linked to infertility." (PMID 33362560, 2020). "In the group of all endometriosis patients we found an elevation of IL-6; however, IL-6RA was significantly decreased compared to controls." (PMID 32604857, 2020). "Interleukin-6 (IL-6) and Interleukin-8 (IL-8) were the only two proteins found to be significantly increased in patients with endometriosis compared to controls—IL-6 was increased 2.13-fold, and IL-8 was increased 2.56-fold, respectively." (PMID 32604857, 2020). "The continuous activation of MCs and the production of IL-4 and IL-6 are related to the production and maintenance of persistent inflammation, leading to deterioration of endometriosis." (PMID 32145751, 2020). "High serum IL-6 concentrations in endometriosis patients are probably related to the reduction in conserved helix-loop-helix ubiquitous kinase (CHUK) protein as well as NF-κB inhibitor alpha (NFKBIA) mRNA and the p-NFKBIA/NFKBIA protein ratio." (PMID 32145751, 2020). "This endometriosis animal model showed a human endometriosis phenotype, such as increased expression levels of Er-β, Ccl2, Ccl5, and Il-6." (PMID 33339236, 2020). "In the last decades, immunological molecules and inflammatory cytokines have been extensively studied for their potential as noninvasive biomarkers for endometriosis, with the most representative being IL-1, IL-6, IL-8, interferon-γ (IFN-γ), MCP-1, and TNF-α." (PMID 32143439, 2020). "The elevated concentrations of IL-6 and IL-8 demonstrate the pro-inflammatory surroundings in the peritoneal cavity of patients with endometriosis." (PMID 32604857, 2020). "Neutrophils in the peritoneal fluid of endometriosis increase the production of VEGF in the presence of IL-6, TNF-α, LPS, and estrogen." (PMID 32334621, 2020). "In the early development stage of endometriosis, acute inflammatory responses and tissue breakdown were induced by pro-inflammatory cytokines such as interleukin (IL)-6, IL-1β, interferon (IFN)-γ, and tumor necrosis factor (TNF)." (PMID 31636643, 2019). "Gene expression analysis showed that endometriosis altered the expression of Cebpa, Cebpb, Ppar-γ, leptin, adiponectin, IL-6, and HSL, which are involved in driving brown adipocyte differentiation, appetite, insulin sensitivity and fat metabolism." (PMID 30982470, 2019). "TNF-α or IL-6 levels in serum and peritoneal fluid samples played a role in endometriosis-related pelvic inflammation." (PMID 31088412, 2019). "Transcriptomic work on endometriomas showed that the inflammatory cytokine transforming growth factor beta 1 (TGFβ1), regulates other inflammatory mediators relevant to endometriosis, including tumor necrosis factor alpha (TNFα) and interleukin-6 (IL6)." (PMID 30087267, 2018). "The present study characterizes the role of miR-17, IL-4, and IL-6 in the pathogenesis of endometriosis, suggesting the feasibility of using miR-17 and selected cytokines as a noninvasive diagnostic test for the detection of endometriosis." (PMID 29901577, 2018). "IL-6 facilitated macrophage M2 polarization in endometriosis, and neutralization of IL-6 diminished this effect." (PMID 30276219, 2018). "Some fibrotic markers such as connective tissue growth factor (CTGF), TGF, and collagen I, and some inflammatory cytokines such as IL-1 and IL-6 are well known to be upregulated in endometriosis models." (PMID 29954457, 2018). "John's wort oils (HrHp oil) significantly decreased the volumes of endometriotic implants and reduced the levels of TNF-α, vascular VEGF and IL-6 in peritoneal fluids in a surgically induced endometriosis rat model." (PMID 30402122, 2018). "The PF of women with endometriosis contains a variety of inflammatory mediators, including Tumor Necrosis Factor α (TNFα), Interleukin-6 (IL-6), and Interleukin-8 (IL-8)." (PMID 31417983, 2018).
endometriosis (continued). "The results showed miR-22 expression decreased along with the higher endometriosis grade significantly whereas the level of IL-4 and IL-6 markedly decreased." (PMID 29901577, 2018). "Both EtOAc and methanol(MeOH)extracts of V. opulus L. showed significant inhibition of TNF-α, VEGF, and IL-6 levels in a rat model of surgically induced endometriosis." (PMID 30402122, 2018). "In order to explore the role of miR-17, IL-4, and IL-6 in the development of endometriosis, the expression of these indexes was analyzed using qPCR." (PMID 29901577, 2018). "While the immediate effect of antalarmin in inflammatory molecules was not the main objective of our current experiments, we recognize that inflammatory activity mainly via TNF-α, IL-6, IL-1β, among others has a significant role in endometriosis." (PMID 30427841, 2018). "And the level of miR-17, IL-4, and IL-6 was analyzed based on different grades in endometriosis group." (PMID 29901577, 2018). "Serum IL-6 levels raised in women with endometriosis are positively correlated with disease stage and change in response to symptom severity during treatment." (PMID 28694989, 2018). "E2/ERα/IL-6-mediated cross talk played a partial role in the early initiation of endometriosis, whereas the IL-6-mediated response was found in developing lesions lacking ERα." (PMID 30276219, 2018). "Elevated pro-inflammatory cytokines IL-1β, TNF-α, and IL-6 are indicative of an inflammatory microenvironment for the follicles and gametes and embryos of endometriosis patients." (PMID 30555421, 2018). "This assumption is supported by similar findings in both endometriosis and GH-PE, including activation of macrophages, increased production of cytokines such as IL-6, TNF-α, lipid peroxidation, and growth factors, and modulated NK cell activity." (PMID 28715497, 2017). "Here, we report that IL-10+Th17 cells are significantly increased in the peritoneal fluid of women with endometriosis, along with an elevation of IL-27, IL-6 and TGF-β." (PMID 28300844, 2017). "Endometriosis patients show elevated levels of different pro-angiogenic factors including IL-8, IL-6, angiogenin, HGF and prostaglandin E2." (PMID 27695098, 2016). "The level of IL-6, another inhibitory cytokine, is dramatically increased in the PF of patients with endometriosis." (PMID 27294113, 2016). "IL-6 possesses prominent inflammatory and anti-inflammatory functions, which makes it challenging to understand its full role in endometriosis." (PMID 26247027, 2015). "In endometriosis patients, the PF levels of IL-6 have been found to be increased compared to normal women and positively correlated with the size and number of endometriotic lesions." (PMID 26247027, 2015). "Increasing levels of IL-1β and TNF-α would induce the production of IL-6 by peritoneal mesothelial cells, which would further contribute to the local inflammation observed in endometriosis." (PMID 26247027, 2015). "A plethora of cytokines has been assessed in the search for a noninvasive diagnosis of endometriosis, including IL-1, IL-6, IL-8, TNF-α, MCP-1, and interferon-γ (IFN-γ)." (PMID 26240814, 2015). "Recently, IL-6 in PF of women with endometriosis has been identified as a possible immunosuppressant towards NK cell cytotoxicity against autologous endometrial fragments." (PMID 26247027, 2015). "Bergqvist and colleagues reported higher levels of IL-6 in both endometriotic lesion and eutopic endometrium from endometriosis patients compared to normal women." (PMID 26247027, 2015). "Studies investigating of serum cytokines as biomarkers have demonstrated significant elevation of levels of interleukin-6, monocyte chemotactic protein-1, and interferon-gamma in serum of subjects with endometriosis compared to healthy women." (PMID 24927773, 2014).
endometriosis (continued). "In fact, increased levels of inflammatory cytokines such as interleukin-6 (IL-6), interleukin-8 (IL-8), and tumor necrosis factor-alpha (TNFα) have been observed in the peritoneal fluid in patients with endometriosis." (PMID 25331066, 2014). "In our study, compared with the disease-free controls, the eutopic endometrium from women with endometriosis showed an increased basal production of IL-6 and TNF-α, which both play a prominent role in a number of chronic inflammatory conditions." (PMID 24173391, 2014). "Underlining the inflammatory nature of the condition is the fact that TNFα, ENA-78, and IL-6 are also elevated in the serum of women with endometriosis." (PMID 24453419, 2013). "The study showed that the mRNA expression of the chemokines ENA-78 and RANTES, as well as the inflammatory cytokines TNFα and IL-6, was significantly increased in the ectopic lesion compared to those in the matched eutopic tissue in women with endometriosis." (PMID 24453419, 2013). "Embryotoxicity reported in the serum and peritoneal fluid of infertile women with endometriosis appears to be related to high levels of IL-6, IL-8, and NK cells in these fluids." (PMID 23956867, 2013). "Cultured human endometrial stromal cells (HESC) from women with endometriosis secrete IL-6 and IL-8 robustly." (PMID 23766765, 2013). "Other molecular alterations in endometriosis, such as the aberrant expression of the active P450 aromatase enzyme and its stimulation by IL-6 or TNF-α, lead to a continuous local supply of estrogen independent of circulating levels." (PMID 23956867, 2013). "Various authors have shown that women with endometriosis have higher peritoneal fluid concentrations of IL-6 compared to those who are normal." (PMID 22536401, 2012). "CA 125, Ca 19.9, ICAM-1, and IL-6 together with follistatin and urocortin have proven to be the most reliable markers for endometriosis diagnosis." (PMID 23093966, 2012). "Indeed, abnormal spindle dynamics mediated by IL-6 elevation is known to lead to aneuploidy, failure of fertilization, early loss of pregnancy, or low reproductive outcome under certain pathological conditions such as in patients with endometriosis and pelvic inflammation." (PMID 22536401, 2012). "MUC2 expression was reported to be regulated by many endometriosis-related cytokines, such as IL-1β, IL-6, TNF-α, NF-Kappa B." (PMID 22417007, 2012). "In a mouse model of endometriosis, it was reported that interleukin-6 (IL-6) together with tumor necrosis factor alpha (TNF-α) was secreted by macrophages, and resulted in upregulation of VEGF from infiltrating neutrophils and macrophages." (PMID 20085636, 2010). "Supporting this scenario is that subjects with endometriosis have significantly higher serum levels of interleukin (IL)-6, monocyte chemotactic protein-1, and interferon-gamma as compared to control women." (PMID 19019211, 2008). "For example, Interleukin-6 (IL-6) and Interleukin-8 (IL-8) have been shown to be elevated in the peritoneal fluid of women with endometriosis, but the reason for this abnormal cytokine expression has not been determined." (PMID 16384532, 2005). "Some studies indicate the role of TNF-α, IL-6, and IL-8 in the development of endometriosis." (PMID 40507929, 2025). "Notably, deep infiltrating endometriosis samples showed the highest IL-6 levels, significantly exceeding those of the patient’s peritoneum (p = 0.0001) and peritoneal endometriosis (p < 0.0001)." (PMID 41516088, 2025). "Interestingly, Il6, Mmp3, Itgb2, and Vegfa, a group of genes known to play a role in endometriosis, increased in the developing lesion tissues in all groups compared with control I and α minced endometrial pieces." (PMID 39836475, 2025). "It has been found that IL-6 may participate in the development of endometriosis by inhibiting the apoptosis of ectopic implants and stimulating the migration of endometriotic implants." (PMID 40507929, 2025).
endometriosis (continued). "Additionally, this study showed that patients with endometriosis had a much higher level of IL-6 expression, which is consistent with findings from other similar studies." (PMID 39822256, 2025). "Patients diagnosed with endometriosis demonstrated significantly heightened levels of inflammatory cytokines, specifically interleukin-1 beta (IL-1β), interleukin-6 (IL-6), interleukin-8 (IL-8), vascular endothelial growth factor, CCL2, CCL5, and tumor necrosis factor-alpha (TNF-α)." (PMID 40303639, 2025). "In cases of endometriosis, however, elevated levels of cytokines in the peritoneal fluid, such as interleukin (IL)-6, IL-1β, IL-8, tumor necrosis factor (TNF)-α, and transforming growth factor (TGF)-β, contribute to the development of a chronically inflamed peritoneal environment." (PMID 40692689, 2025). "IL-6, a central driver of chronic inflammation, disrupts ovarian folliculogenesis, endometrial receptivity, and follicular survival, particularly in conditions of endometriosis and PCOS." (PMID 41227338, 2025). "Finally, IL-6 levels were found to be highest in patients with endometriosis and chronic pelvic pain compared to those with endometriosis without chronic pelvic pain and to control women undergoing laparoscopic tubal ligation (n = 85 cases and 53 controls)." (PMID 40508188, 2025). "IL-1 generally regulates inflammation and, together with TNF-α and IL-6, has been found to promote multiple aspects of endometriosis, including inflammation, nerve growth factor expression, angiogenesis, and the growth and adhesion of ectopic endometrial tissue." (PMID 40724945, 2025). "Therefore, all three inflammatory parameters (suPar, hepcidin, IL-6) collected in the studies were included in a further machine learning classification for the diagnosis of endometriosis." (PMID 40542028, 2025). "The peritoneal fluid in women with endometriosis contains increased concentrations of activated macrophages and elevated levels of pro-inflammatory cytokines and chemokines, including interleukin-6 (IL-6)." (PMID 40142712, 2025). "Additionally, they found that TNF-α and IL-6 levels were reduced in Alchemilla-treated endometriosis group." (PMID 40550985, 2025). "In sharp contrast, in the presence of FF-ENDO, none of the three GC groups expressed IL-6 levels higher than 100, suggesting that endometriosis-associated follicular fluid strongly restricts IL-6 production." (PMID 41463303, 2025). "All endometriosis forms share core immunopathogenetic mechanisms: macrophage accumulation with M2 polarization, reduced NK cytotoxicity, elevated pro-inflammatory cytokines (IL-1β, IL-6, TNF-α) alongside immunosuppressive mediators (IL-10, TGF-β)." (PMID 41488658, 2025). "IL-6 is increased in the endometrium of women with endometriosis and in ectopic lesions." (PMID 38892003, 2024). "While abundant cytokines and chemokines have been observed in the pelvic cavity of endometriosis patients, TNFα, IL-1β, and IL-6 are considered the key factors involved in maintaining the aberrant peritoneal inflammatory environment, promoting lesion growth, and mediating peripheral sensitization." (PMID 39192982, 2024). "In the pathogenesis of endometriosis, an inflammatory gynecological disease in female reproduction, the higher level of IL-6 produced by the macrophages and local epithelial cells leads to up-regulation of NOTCH1 expression and the hyper-proliferation of the ectopic tissue." (PMID 38538986, 2024). "Additionally, they observed a positive correlation between IL-6 levels in serum and peritoneal fluid and the severity of endometriosis." (PMID 39767772, 2024). "Increased levels of IL-6 have been observed in patients with endometriosis." (PMID 39597051, 2024). "Moreover, the utilization of a comprehensive panel of serum markers, including Ca-125 and interleukin 6 and 8, has yielded promising outcomes in the diagnosis of mild to moderate endometriosis." (PMID 39202622, 2024).
endometriosis (continued). "Several studies have shown elevated levels of IL-6 in peritoneal fluid of patients with endometriosis, which led us to investigate whether the expression of miR-21, via STAT3, is induced by IL-6." (PMID 39201680, 2024). "Some studies have shown that a higher consumption of fruits and green vegetables may be protective because it can reduce inflammatory markers such as IL-6, which are thought to be involved in the pathogenesis of endometriosis." (PMID 38540637, 2024). "IL-1 is a pleiotropic cytokine that may promote the development of endometriosis in the peritoneal cavity, upregulating the expression of other cytokines such as IL-6 or other growth factors." (PMID 38892003, 2024). "Additionally, intraperitoneal injection of LPS (50 μg/body) increased the mRNA expression of VEGF and IL-6 in mice with surgically induced endometriosis-like lesions via the NF-κB pathway." (PMID 38612685, 2024). "First, IL-6 is elevated in the peritoneal fluid and the serum of patients with endometriosis." (PMID 39141428, 2024). "The proinflammatory role of IL-6 in endometriosis is supported by several lines of evidence." (PMID 39141428, 2024). "We also investigated the effect of IL-6 in vivo using the mouse model of endometriosis." (PMID 39201680, 2024). "Additionally, IL-6, which is strongly expressed by macrophages, influences cell migration, a key factor in the development of endometriosis." (PMID 39001478, 2024). "Mast cell tryptase might accelerate endometriosis by increasing the number of endometriotic stromal cells and IL-6 and IL-8 secretion." (PMID 38778076, 2024). "Endometriosis shares a common inflammatory pathogenesis with cancers, involving TNF-alpha, IL-1, IL-6, IL-8, and VEGF, associated with retrograde menstruation, iron overload, and the activation of macrophages, triggering aberrant inflammatory signaling and impairing phagocytic potential." (PMID 38337827, 2024). "The interplay between TET3 and IL-6 suggests that TET3-overexpressing macrophages may drive the inflammatory response in endometriosis by modulating IL-6 signaling." (PMID 39484721, 2024). "In addition, our findings align with other recent studies that showed that a persistent activation of STAT3 via IL-6 signaling is involved in fibrosis in endometriosis." (PMID 39201680, 2024). "The exposure of IL-6 may inflict the stem cells that shed along with retrograde menstrual effluent to migrate, invade, and establish endometriosis at ectopic sites." (PMID 38765018, 2024). "In addition, B cells secrete cytokines, including IL-6, interferon γ (IFNγ), and IL-17, which also contribute to the inflammatory processes in endometriosis." (PMID 37834449, 2023). "In addition, upregulation of MAPK subfamilies promoted the occurrence of endometriosis by influencing the function of various cytokines, including IL-6 and IL-8." (PMID 36660246, 2023). "Cytokines and inflammatory mediators such as IL-1, IL-6, IL-8, IL-12, IFN-γ, MCP-1, TNF-α, sTNFR-1, and CCL5 (RANTES), which are measured in the serum and PF of patients with endometriosis, have the potential to serve as diagnostic biomarkers in patients with endometriosis." (PMID 36865552, 2023). "Curcumin, an antioxidant and anti-inflammatory agent, can reduce the expression of ROS and NO to suppress oxidative stress and inhibit the NF-κB pathway and the expression of TNF-α, IL-1, IL-6, and IL-8 in macrophages of mouse models; thus, it has a potential therapeutic effect on endometriosis." (PMID 36865552, 2023). "In this report, the absence of a correlation between the follicular levels of IL6 and AMHf supports the fact that the inflammatory process caused by endometriosis does not affect the intrafollicular endocrine environment and consequently the ovarian reserve." (PMID 36902616, 2023). "These processes may be involved in some of the changes in inflammatory markers seen in endometriosis, including raised levels of IL-6 and dysfunction of macrophages." (PMID 38002684, 2023).